CTLA4 (cytotoxic T-lymphocyte associated protein 4)
Diseases named in the same sentence as CTLA4 in open-access papers (continued):
Sharing a sentence is not in itself a finding about the gene and the disease.
cancer (continued). "ICIs targeting CTLA-4 and PD-1 have improved cancer immunotherapies; however, other checkpoint receptors are also identified as essential for broadening therapeutic responses." (PMID 40567374, 2025). "Since the first FDA approval of anti-CTLA-4 (Ipilimumab) in 2011, cancer immunotherapies have rapidly evolved, with more than half a dozen ICIs approved and numerous combination regimens under clinical evaluation." (PMID 40605058, 2025). "We then reviewed cross-sectional surveys, early-phase trials, and large-scale phase II and II clinical trials that reported HRQL measures in cancer patients receiving PD-1, PD-L1, or CTLA-4 inhibitors." (PMID 41463169, 2025). "Immunotherapeutic modalities—including checkpoint inhibitors (PD-1/PD-L1, CTLA-4), CAR-T and CAR-NK cell therapies, cytokine-based treatments (e.g., IL-2, TNF-α), cancer vaccines, and oncolytic viruses—are all susceptible to immune remodeling induced by μg." (PMID 40940834, 2025). "In line with increased infiltration of cluster #2 cancers by T cells, clinically relevant immune checkpoint genes CTLA4, TIGIT, and PDCD1 were found to be expressed in this cluster at the highest levels." (PMID 40011822, 2025). "Studies on murine leukemia cells confirm the role of CTLA-4 in preventing cancer cells from escaping the immune response." (PMID 40574024, 2025). "The emergence of PD-1/PD-L1/CTLA-4 inhibitors undoubtedly provide a new ray of hope for curing cancer, yet the response rate of patients remains disappointingly low." (PMID 41459523, 2025). "A recent study showed dual inhibition of PD‐L1 and CTLA‐4 contributed to cancer growth arrest and completely blocked distant metastasis, while inhibition of PD‐L1 and CTLA‐4 alone modestly reduced the metastatic spread of malignant cells." (PMID 40778650, 2025). "According to our included studies, ICIs including PD-1, CTLA-4, and PD-L1 inhibitors were used to treat cancers in KT recipients, either as mono- or combined therapies." (PMID 40725844, 2025). "Anti-CTLA-4 antibodies in cancer therapeutics can bind CTLA-4 with high affinity and block the binding to CD80 and CD86." (PMID 40227644, 2025). "Several CTLA-4 inhibitors have shown promising potential in enhancing T cell immune responses and improving treatment outcomes in cancer therapy." (PMID 40739089, 2025). "Whilst showing robust and durable immune protection in cancer patients, the clinical benefits of CTLA4 blockade are often overshadowed by severe immunotherapy-related adverse events (irAEs) that highly resemble autoimmune reactions." (PMID 39404738, 2025). "For the first time, we reveal positive correlations between SGO1 expression and immune checkpoint genes (PD-1, PD-L1, CTLA4) in most cancers." (PMID 40861810, 2025). "Oncogenic pathways, inflammatory signaling, and epigenetic mechanisms influence the regulation of CTLA-4 expression and PD-L1 at the Ribonucleic Acid (RNA) level, fostering a version of immunity in cancer." (PMID 39996755, 2025). "Checkpoint inhibitors targeting CTLA-4 and PD-1 revolutionized the treatment of cancer patients, but their use is limited by the emergence of immune-related adverse events (irAEs)." (PMID 41026527, 2025). "In this study, the therapeutic potential of CTLA-4 blockade in canine cancers was investigated through the development of a caninized anti-CTLA-4 antibody, ca1C5, designed to block ligand binding to canine CTLA-4." (PMID 40463388, 2025). "Recent studies have underscored the critical role of CTLA4 in immune evasion in a variety of cancer types, including skin cancers." (PMID 40005446, 2025). "Recent developments in cancer immunotherapy have introduced immune checkpoint inhibitors (ICIs) that target inhibitory receptors on T cells, such as PD-1 and CTLA-4, thus enhancing the immune system’s ability to eliminate cancer cells." (PMID 40071095, 2025).
cancer (continued). "Consistent with murine studies, well-known Tex genes (CTLA4, LAG3, HAVCR2 (gene encoding Tim-3), PDCD1, TIGIT, TOX) were among the most prominently represented in Tex from human cancers." (PMID 40236693, 2025). "The use of immunotherapy to boost T cell activity against cancer cells, such as through the blockade of CTLA-4, PD-1 or PD-L1, has been shown to have beneficial effects in AGC patients." (PMID 39996912, 2025). "In parallel, dual-targeting strategies that integrate metabolic inhibition with PD-1/PD-L1 or CTLA-4 blockade are under investigation in multiple cancer types, including non-small cell lung cancer, hepatocellular carcinoma, and ovarian cancer." (PMID 41562065, 2025). "Immune checkpoint blockade (ICB), particularly targeting CTLA-4 or PD-1/PD-L1, has significantly advanced cancer treatment, offering clinical benefits across various cancers, including melanoma, NSCLC, and renal cell carcinoma." (PMID 40361472, 2025). "The complementary mechanisms of action of PD-1/PD-L1 and CTLA-4 inhibitors have demonstrated synergistic effects, improving response rates, overall survival, and progression-free survival in various cancer types." (PMID 41159031, 2025). "In recent years, immune checkpoint inhibitors (ICIs), which target cytotoxic T-lymphocyte antigen-4 (CTLA-4), programmed cell death 1 (PD-1) and programmed cell death ligand-1 (PD-L1), have shown significant efficacy in treating various malignant tumors." (PMID 40963607, 2025). "In humans, ICIs targeting cytotoxic T-lymphocyte associated protein 4 (CTLA-4) and the programmed death 1 (PD-1)/PD ligand 1(PD-L1) axis have demonstrated clinical activity in several cancers." (PMID 39943162, 2025). "In contrast, this elevation in CTLA-4 affects various other systemic immuno-inflammatory disorders, predominantly cancer and the efficacy of its immunotherapy." (PMID 41395347, 2025). "This retrospective cohort study on CTLA-4-treated patients showed that immune-related adverse event incidence correlated with improved cancer outcomes, similar to that seen in PD-1-treated patients." (PMID 40563660, 2025). "In recent years, cancer immunotherapy, including ICIs such as anti‐CTLA‐4 and anti‐PD‐1/PD‐L1 antibodies, has made remarkable progress." (PMID 40538456, 2025). "Programmed cell death-1/programmed cell death ligand-1 (PD-1/PD-L1) and cytotoxic T-lymphocyte-associated antigen 4 (CTLA-4) blockers and other ICI have been listed as standard treatment options for multiple types of cancer." (PMID 41357573, 2025). "In cancer, Tregs become overproduced, and they then overexpress CTLA-4, which inhibits the activation and proliferation of effector T cells." (PMID 40805190, 2025). "As binding of PDL-1 and CTLA-4 with their receptors act as an “off switch” signal for hindering T cells from attacking harmful cells including cancer cells." (PMID 40108523, 2025). "We conducted a retrospective analysis of clinical data from 3,489 cancer patients treated with ICIs (anti-PD-1, anti-PD-L1, and anti-CTLA-4) at West China Hospital of Sichuan University from 2017 to 2022." (PMID 40124377, 2025). "In recent years, CTLA-4 has emerged as a crucial target in immune checkpoint-based therapies, particularly in cancer treatment, through the use of monoclonal antibodies targeting the CTLA-4 molecule." (PMID 41357215, 2025). "In OC-TME, elevated IL6 levels upregulate the expression of PDL1 and CTLA4 in cancer cells, which inhibits T cell activity and serves to escape the immune response." (PMID 40427188, 2025). "ICI like Nivolumab, Pembrolizumab (anti-PD-1), Atezolizumab, Avelumab (anti-PD-L1), and Ipilimumab (anti-CTLA-4) block these inhibitory checkpoints and enable T-cells to attack cancer cells." (PMID 40260236, 2025). "Starting with the approval of anti-cytotoxic T lymphocyte-associated antigen 4 (CTLA-4) and programmed death-1 (PD-1) gained by FDA, immune checkpoint inhibitors (ICIs) have made indelible achievements in cancer immunotherapy." (PMID 39744687, 2025).
cancer (continued). "Immunomodulatory strategies, including immune checkpoint inhibitors (anti‐PD‐1/PD‐L1), CTLA‐4 blockers, adoptive T‐cell therapy, and cancer vaccines, stimulate immune response against cancer cells." (PMID 41049266, 2025). "When combined with immunogenic checkpoint inhibitors (like anti-PD-1, anti-PD-L1, or anti-CTLA-4), the blockade would potentially synergize with T-cell activation, proliferation, and cancer cell killing." (PMID 40867265, 2025). "These strategies involve various approaches including the use of immune checkpoint inhibitors, CTLA‐4 inhibitors, adoptive T‐cell therapy, and cancer vaccines." (PMID 41049266, 2025). "Immune checkpoint inhibitors (ICIs), such as anti-PD-1/PD-L1 and anti-CTLA-4 therapies, have shown substantial clinical benefits in many types of cancer." (PMID 41244914, 2025). "This review presents and discusses results from clinical studies evaluating PD-1/PD-L1 and CTLA-4 inhibitor combinations, highlighting current achievements, clinical limitations, and future directions in cancer immunotherapy." (PMID 41159031, 2025). "The introduction of immune checkpoint inhibitors, such as anti-CTLA-4 (ipilimumab) and anti-PD-1 (nivolumab, pembrolizumab), has demonstrated significant clinical success in treating various cancers, including melanoma, lung cancer, and renal cell carcinoma." (PMID 40507229, 2025). "The anti-cancer effect of anti-CTLA-4 relied on Bacteroides species, particularly Bacteroides fragilis." (PMID 40352591, 2025). "Immune checkpoint inhibitors, such as those targeting PD-1, PD-L1, and CTLA-4, have led to breakthrough responses in several cancers." (PMID 40755757, 2025). "Immunotherapy with antibodies against cytotoxic T-lymphocyte-associated protein 4 (CTLA4), programmed death-1(PD-1), and PD-L1 has been shown to be clinically effective and is used in treating various types of cancers." (PMID 40632765, 2025). "The advent of ICIs, including anti-PD-1, anti-PD-L1, and anti-CTLA-4 antibodies, represents a landmark shift in cancer therapy." (PMID 40963596, 2025). "Cadonilimab, a novel anti-PD-1/CTLA-4 bispecific antibody, has shown substantial clinical benefits in cancer treatment." (PMID 40726978, 2025). "The last 10 years have witnessed transformative advances in cancer treatment, with immune ICIs targeting PD‐1/PD‐L1 and CTLA‐4 pathways demonstrating unprecedented clinical efficacy across multiple malignancies." (PMID 40672434, 2025). "While elimination of immunological barriers by PD-1/CTLA4 blockade has yielded improved responses to some cancers, immune cells are still inhibited by the biochemical barriers derived from oxygen-poor and extracellular adenosine–enriched TMEs." (PMID 40125552, 2025). "In chronic infections (e.g., HIV, HCV) and cancer, multiple coinhibitory receptors, including PD-1, CTLA-4, LAG-3, TIM-3, and TIGIT are upregulated on Tex." (PMID 40236693, 2025). "Immune checkpoint inhibitors (ICIs), such as antibodies targeting PD-1, PD-L1, or CTLA-4, have become effective treatment options for a variety of cancers." (PMID 41561746, 2025). "Animal experiments related to Coprobacter have shown that this bacterium enhances the efficacy of immune checkpoint blockade (ICB) therapy, modulating CTLA‐4 or PD‐L1, pointing to a new direction for future cancer treatments." (PMID 41384027, 2025). "Blocking the CTLA-4 checkpoint can restore the initiation and activation of T cells to attack cancer cells." (PMID 40169560, 2025). "Several monoclonal antibodies blocking immune checkpoints such as Programmed cell Death-1 (PD-1), Programmed Death-Ligand 1 (PD-L1), Cytotoxic-T-Lymphocyte Antigen-4 (CTLA-4) have already been approved for the treatment of different types of cancer." (PMID 41041320, 2025). "Clinical trials involving antibodies such as ipilimumab and nivolumab, aimed at CTLA-4 and PD-1/PD-L1 respectively, demonstrated lasting responses in melanoma and other cancers." (PMID 40352591, 2025).
cancer (continued). "The approval of tremelimumab not only adds a new agent to the CTLA‐4 mAb family but also paves the way for future advancements in cancer immunotherapy." (PMID 40415479, 2025). "Among ICIs, those that target PD-1 and CTLA-4 have been widely adopted in clinical practice, offering significant therapeutic benefits for many cancer patients." (PMID 40775249, 2025). "ICIs targeting the PD-1/PD-L1 and CTLA-4 axes have redefined systemic therapies, offering durable responses in patients with advanced cancers." (PMID 40075730, 2025). "The U.S. Food and Drug Administration (FDA) has approved several ICIs that target PD-1, PD-L1, and CTLA-4 for various cancers." (PMID 41239350, 2025). "In recent years, remarkable progress has been achieved in the field of cancer immunotherapy, particularly through the development and application of immunotherapeutic agents that primarily focus on the CTLA-4, PD-1, and PD-L1 immune checkpoint pathways." (PMID 40224950, 2025). "It is noteworthy that ICIs, such as anti-CTLA-4 and anti-PD-1 monoclonal antibodies (mAbs), have demonstrated considerable efficacy in treating various types of cancer." (PMID 40075727, 2025). "Treme targets cytotoxic T-lymphocyte antigen 4 (CTLA-4) and activates T cells by blocking the actions of CTLA-4, thereby enhancing the immune responses against cancer cells and inducing cancer cell death." (PMID 39895083, 2025). "In different CTLA-4 expressing cancer cell lines, CTLA-4 signaling was able to modulate apoptosis, migration and EMT." (PMID 40175626, 2025). "Immune checkpoint inhibitors (ICIs) such as anti-PD-1/PD-L1 and anti-CTLA4 antibodies have shown impressive clinical outcomes across various cancers." (PMID 41425568, 2025). "Nonetheless, the clinical effectiveness of anti-CTLA-4 therapy is constrained and confined to a certain group of cancer patients." (PMID 41233805, 2025). "Of note, dual blockade immunotherapy targeting PD-1/PD-L1 and CTLA-4 has achieved remarkable success in various cancers." (PMID 40732268, 2025). "Dual blockade using monoclonal antibodies (mAbs) targeting PD-1/PD-L1 and CTLA-4 has shown synergistic effects, improving response rates, overall survival, and progression-free survival in several cancer types." (PMID 41159031, 2025). "Immune checkpoint blockade (ICB) therapy based on antibody-mediated blockade of key checkpoint molecules, such as cytotoxic T lymphocyte-associated protein 4 (CTLA-4) and programmed cell death protein 1 (PD-1), have achieved clinical success in some cancers." (PMID 39126156, 2025). "In other cancers, therapies involving CTLA‐4 or PD‐L1 inhibitors have demonstrated that Eastern Cooperative Oncology Group PS 2 is associated with poor prognosis." (PMID 40856425, 2025). "They enhance the immune response by blocking inhibitory signals (PD-1, CTLA-4) that prevent T cells from attacking cancer cells, thereby reactivating the immune system to target thetumor." (PMID 40630962, 2025). "Recent evidence suggests that the gut microbiome plays a crucial role in influencing responses to immune checkpoint inhibitors (ICIs), such as anti-PD-1 and anti-CTLA-4 therapies, which are widely used in cancer treatment." (PMID 40364844, 2025). "Ipilimumab’s CTLA-4 blockade has been transformative in the evolution of cancer immunotherapy, reshaping treatment paradigms for difficult-to-treat malignancies." (PMID 40940902, 2025). "B7-H3 is an inhibitory checkpoint molecule similar to CTLA-4 and PD-1 that has been studied in the context of auto-immune diseases and cancer, where it was shown to be a key inhibitor of T cell proliferation." (PMID 39857692, 2025). "Here, we set out to develop such scaffolds and to use them to design high-affinity binders to three key cancer immunotherapy-related receptors: TGFbRII, CTLA-4, and PD-L1." (PMID 40011465, 2025). "ICIs such as PD-1 and CTLA-4 antibodies have demonstrated impressive effectiveness in a variety of malignancies." (PMID 40230883, 2025).
cancer (continued). "Immune checkpoint inhibitors (ICIs), which block regulatory proteins like PD-1, PD-L1, or CTLA-4 to enhance T-cell activation and enable immune responses against cancer, are significantly influenced by circadian rhythms." (PMID 41415271, 2025). "The advent of T-cell-centered immunotherapies, such as PD-1 and CTLA-4 inhibitors, has significantly reshaped treatment paradigms across various cancers." (PMID 40963599, 2025). "Immune checkpoint inhibitors (PD-1, PD-L1, CTLA-4) enhance the immune system’s ability to fight cancer and have been approved for various cancers." (PMID 39757310, 2025). "OC cells can impact on the anti-cancer function of CD8+ T cells through signaling pathways including CTLA-4, PD-1, LAG-3 or TIM-3." (PMID 40136652, 2025). "This study mainly focuses on cancer monotherapy and combination therapy using anti‐CTLA‐4/PD‐1/PD‐L1." (PMID 40243372, 2025). "Immune checkpoint inhibitors (ICIs) such as PD1, PDL1, and CTLA-4 have revolutionized cancer treatment and have benefited patients with different types of cancers." (PMID 39941980, 2025). "Highly immunogenic tumors commonly develop adaptive immune resistance by exploiting these checkpoints to evade immune surveillance, upregulating PD-L1 and CTLA-4 in cancer cells." (PMID 41228294, 2025). "Checkpoint-blocking antibodies, including anti-CTLA-4 and anti-PD-1 therapies, have demonstrated promise in overcoming resistance mechanisms in cancer immunotherapy." (PMID 41008611, 2025). "While immune checkpoint inhibitors targeting PD-1/PD-L1 and CTLA-4 have revolutionized cancer treatment, resistance to these drugs poses a challenge." (PMID 40739089, 2025). "Anti–PD-1 therapy led to more successful clinical outcome compared with anti–CTLA-4 therapy in some cancer types, including renal cancer, lung cancer, melanoma and lymphoma." (PMID 41026527, 2025). "Within the TME, an increased expression of two immunological checkpoints, namely programmed cell death protein 1 (PD-1) and cytotoxic T lymphocyte-associated protein 4 (CTLA-4), was detected in T cells in most kinds of cancer." (PMID 40149640, 2025). "Immune checkpoint inhibitors (ICIs), which reinvigorate exhausted T cells by blocking inhibitory pathways such as PD-1/PD-L1 and CTLA-4, have achieved remarkable success in treating certain cancers." (PMID 40660400, 2025). "Combining cancer vaccines with immune checkpoint inhibitors, such as anti-PD-1 and anti-CTLA-4, has shown potential in boosting the efficacy of vaccines by blocking inhibitory signals and promoting T cell responses." (PMID 40660400, 2025). "HDTs have dramatically changed the treatment and outcomes of specific cancers (i.e. checkpoint inhibitors such as anti-PD1 or anti-CTLA4 antibodies); unfortunately, their use in infectious diseases has limitedly reached clinical practice." (PMID 40606628, 2025). "The advent of ICIs has revolutionized cancer treatment, particularly with the success of agents targeting PD-1, PD-L1, and CTLA-4." (PMID 41471273, 2025). "Studies have demonstrated a correlation between CTLA-4 expression and the survival rate of cancer patients, including those with non-small cell lung cancer (NSCLC), suggesting its potential as a prognostic marker in cancer treatment." (PMID 40006624, 2025). "Given their functions, combination therapy with anti-PD-1, anti-PD-L1, and anti-CTLA-4 inhibitors has become an intriguing approach to cancer treatment." (PMID 39941829, 2025). "Immune checkpoint inhibitors such as CTLA4 monoclonal antibodies (e.g., ipilimumab, tremelimumab) are increasingly used to treat various cancers." (PMID 39934899, 2025). "Immune checkpoint inhibitors (ICIs), including anti-PD-1, -PD-L1 and -CTLA-4 antibodies, have revolutionized cancer therapy." (PMID 41438755, 2025). "Tremelimumab is a fully humanized anti-CTLA-4 mAb which blocks the signaling pathway that helps cancers evade immune scrutiny." (PMID 39923010, 2025).